STAT3 (signal transducer and activator of transcription 3)
Diseases named in the same sentence as STAT3 in open-access papers (continued):
Sharing a sentence is not in itself a finding about the gene and the disease.
tumor (continued). "Strategies to block STAT3 activation in tumor cells include direct binding to the SH2 domain that is responsible for STAT3 dimerization and phosphorylation, or indirect inhibition of upstream tyrosine kinases." (PMID 36509291, 2022). "Here, we provide an overview of the role of STAT3 in the dynamic interplay between NK cells and tumor cells." (PMID 35865518, 2022). "H182 and H172 therefore represent suitable candidates for further PK optimization towards the goal of clinical development for treating TNBC and other tumors that are dependent on aberrantly-active Stat3 for the tumor phenotype." (PMID 35276290, 2022). "As another critical STAT3 phosphorylation site, p-STAT3 (Tyr705) interacts with programmed death ligand 1 to facilitate tumor necrosis." (PMID 36443287, 2022). "Vascular endothelial growth factor (VEGF), one of the target genes downstream of STAT3, was significantly elevated in tumor tissues and tissues with lymph node metastases." (PMID 36291659, 2022). "It plays a critical role in transcriptional regulation of genes that are involved in tumor cell proliferation, survival, migration and invasion into the extracellular matrix; constitutive activation of STAT3 is observed in 72.4% of human HCC58." (PMID 36284117, 2022). "Recently, STAT3 has gained significant attention for its transcriptional activity and role in inflammation, tumor progression, ischemia-reperfusion injury, and stem cell self-renewal." (PMID 36313702, 2022). "In NPC, IL6 activates JAK2/STAT3 signaling pathway to promote tumor progression, thus affecting the prognosis of patients." (PMID 36506508, 2022). "They contribute to cancer cell survival, proliferation and resistance to apoptosis, STAT3 has been demonstrated to have additional functions in the tumor microenvironment and immune escape of cancer cells." (PMID 35326392, 2022). "It is also known that downstream JAK-mediated STAT3 signaling in both tumor cells and immune cells contributes to tumorigenesis, whose activity has also been associated with drug resistant tumors." (PMID 35159191, 2022). "The acute inflammatory signature observed during early involution, in which Stat3 has a pivotal role, has also been described as tumor promotional." (PMID 35044452, 2022). "The proliferation and viability of macrophages were reported to be enhanced by STAT3 activation, the immune tolerance of CC cells, and inhibition of extracellular matrix remodeling, thereby playing tumor-promoting roles." (PMID 36618366, 2022). "In Epstein–Barr virus (EBV)-infected nasopharyngeal epithelial cells, the responses to interleukin (IL)-26-induced signal transducer and activator of transcription 3 (STAT3) activation were enhanced to promote tumor progression." (PMID 36551991, 2022). "The activation of the signal transducer and the activator of the transcription 3 (STAT3) signaling pathway is an indication of tumor survival and cell proliferation." (PMID 35267408, 2022). "At the same time, the synthesis of kinases, including AKT, phosphoinositide 3-kinase (PI3K), ERK, STAT3, and the mammalian target of rapamycin (mTOR), were significantly reduced in both tumor cell types when co-cultivated with MSCs." (PMID 35741334, 2022). "Another group demonstrated that blocking or silencing Stat3 increased the sensitivity to anoikis in NPC cells, besides that knockdown Stat3 also reserved tumor invasive properties and inhibited expression of CD44." (PMID 36678534, 2022). "It was reported that STAT3 can induce abnormal proliferation of tumor cells through regulation of BCL-2, FAS, survivin and CyclinD1." (PMID 35513871, 2022). "It has also been shown independently that STAT3 inhibition induces RCC tumor cell apoptosis and reduces the number of immunosuppressive cells." (PMID 35562668, 2022).
tumor (continued). "Pharmacological inhibition of the ERK/STAT3 axis with selumetinib or static or the Gpr132 protein hampered lactate-induced M2 macrophage polarization and showed significant anti-tumor effects in preclinical studies." (PMID 35664746, 2022). "In a previous study, EGFR was hyperphosphorylated in 4 out of 5 tumours from patients with acquired or intrinsic resistance to vemurafenib, leading to a hyperactivation of the STAT3 pathway." (PMID 36084109, 2022). "IL-6 activates its receptor and the JAK2/STAT3 pathway, which can lead—in the tumor cells—to increased proliferation, survival and epithelial-mesenchymal transition." (PMID 35804810, 2022). "The activated γδ T cells were necessary for the IL-17/signal transducer and activator of transcription 3 (STAT3) pathway and promoted M2-tumor-associated macrophage (TAM) infiltration in OSCC proliferation." (PMID 36000726, 2022). "The transcription factor STAT3 is a key transcription factor active in both TAMs and MDSCs, whose targeting can rescue anti-tumor immune responses." (PMID 35158779, 2022). "Augmented tumor cell-intrinsic STAT3 signaling activity promotes tumor progression as well as tumor-extrinsic immunosuppressive effects." (PMID 35836213, 2022). "Further research on this topic has revealed that IL-6 activates the STAT3 signaling pathway of tumor cells and promotes the expression of VEGF, thereby inducing angiogenesis." (PMID 35734400, 2022). "Many studies imply that IL-22 exerts its tumor-promoting effects directly by inducing a STAT3-mediated signal cascade in the malignantly transformed hepatocytes." (PMID 36551508, 2022). "STAT3 is constitutively phosphorylated in GBM and inhibition of STAT3 strongly attenuates GBM-driven tumor growth showing that GBM cells are addicted to STAT3." (PMID 40396025, 2022). "Activated STAT3 promotes the expression of proangiogenic and immunosuppressive factors in cancer cells and is essential for tumor progression." (PMID 35244291, 2022). "In studies addressing the significance of STAT3 in CRC, STAT3 activation in different cell types including tumor cells and myeloid cells has been connected to the promotion of tumor development." (PMID 35326623, 2022). "A growing body of evidence indicates that the activation of the JAK2/STAT3 signaling pathway by chemokines or cytokines plays a positive role in tumor growth and progression." (PMID 35155249, 2022). "Constitutive activation of STAT3 plays an important role in tumor formation, development, metastasis, and recurrence." (PMID 35356799, 2022). "Activation of STAT3 signaling is well recognized in several cancers and promotes tumor cell proliferation, survival, invasion and immunosuppression." (PMID 35463323, 2022). "It strongly inhibited STAT3 and suppressed tumor angiogenesis by blocking the signal transducer and activator of transcription 3 (STAT3) activity, as well as the vascular endothelial growth factor (VEGF) and hypoxia-inducible factor-1α (HIF-1α) expression." (PMID 36359936, 2022). "When STAT3 is aberrantly activated in tumours, STAT3 selectively and directly interacts with Smad3, sequesters Smad3 from the Smad nucleoprotein complex and thus antagonizes TGF-β signalling." (PMID 35655269, 2022). "The excessive activity of the NF-κB/IL-6/STAT3 axis results in c-Myc and cyclin D1 overexpression, metabolic disorders, tumor growth, progression, and chemoresistance acquisition." (PMID 35884974, 2022). "Our research also imply that E6 has a broad influence on cytosolic DNA sensing pathway, interferon-induced antiviral module, STAT3 targets, tumor differentiated, tumor evasion, and tolerogenicity." (PMID 36591476, 2022). "Previous studies suggested that the activation of FAK/ERK or JAK2/STAT3 signaling mediated the pro-tumor activities of CKAP2." (PMID 35853854, 2022). "In in vitro experiments, a low concentration of nintedanib (1 μM) can promote STAT3 phosphorylation in different tumor cell lines." (PMID 34976211, 2022).
tumor (continued). "Tumor cells treated with STAT3 inhibitors exhibit lower c-Myc expression in vitro, co-induce cell invasion, and apoptosis, and inhibit tumor in xenografts." (PMID 35113040, 2022). "LncRNA TSLNC8 (tumor-suppressive lncRNA on chromosome 8p12) inhibits phosphorylation of STAT3 (signal transducer and activator of transcription 3) in HCC by inactivating the IL-6/STAT3 signaling pathway." (PMID 36004931, 2022). "IL-6 and downstream activation of JAK2/STAT3 signaling play critical roles in tumor progression, establishment of a stem-like phenotype, and drug resistance." (PMID 35729402, 2022). "The protein levels of STAT3 and IL-6, the activator of STAT3 pathway, were significantly higher in the tissues adjacent to tumor from M2- and M3-injected mice, compared to their expression in the livers of WT counterpart-injected mice." (PMID 35805045, 2022). "Combined inhibition of JAK1,2/STAT3-PD-L1 signaling pathways has been found to suppress CRPC immune escape to NK cell anti-tumor activities." (PMID 36338516, 2022). "It has been reported that activation of the IL-6/STAT3 pathway downregulates the expression of genes to promote tumor angiogenesis." (PMID 36286020, 2022). "Relevant studies have reported that in prostate cancer and gastric cancer, excessive accumulation of ROS can inhibit the STAT3 signaling pathway and exert an anti-tumor effect." (PMID 36371217, 2022). "STAT1, STAT3 and STAT5 also possess tumour suppressive action in certain mutational and cancer type context." (PMID 35229974, 2022). "In a study of the relationship between MIC-1 and tumour progression, MIC-1 was reported to induce tumour progression via STAT3 activation, and STAT-3 signalling was shown to prevent tumour cell apoptosis." (PMID 35948981, 2022). "Especially signaling by the JAK/STAT3 pathway cascade was found to majorly contribute to carcinogenesis by impacting tumor cells as well as the tumor microenvironment that is essential for cancer progression." (PMID 36185259, 2022). "IL-20 subfamily cytokines have been shown to activate the JAK1/STAT3 signaling pathway, which plays a crucial role in cancer cell proliferation and tumor progression." (PMID 36006737, 2022). "In bladder cancer, the tumor-associated dendritic cells were found to secrete CXCL9, increasing PD-L1 expression in the tumor cells via the CXCR3/STAT3/AKT signaling pathway, thus resulting in the inhibition of anti-tumor adaptive immunity." (PMID 36131933, 2022). "To examine the significance of upstream genes involved in STAT3 activation regulating properties of tumor spheroids, we knocked down FN1, ITGA5, JAK1, JAK2, LDB1, and LMO2 from the cells." (PMID 36359204, 2022). "The same behavior happens when the M2-associated transcription factors are disturbed (STAT3 or STAT6); cycle attractors will prevent a hyper-regulation scenario implicated in providing a suitable environment for tumor growth." (PMID 36544764, 2022). "Various types of cancers show hyperactivation of STAT3 by tyrosine 705 phosphorylation, which greatly contributes to tumor development." (PMID 36227136, 2022). "APE1 was shown to mediate tumor progression through activation of various MAPK signaling cascade components such as STAT3, Src and ERK." (PMID 36045416, 2022). "The tumor-suppressive role of PTPN11 in HCC is mediated through the IκB kinase/NF-κB (IKK/NF-κB) pathway through promoting IL-6-stimulated Stat3 activation." (PMID 35057034, 2022). "STAT3 activation contributes to enhancement of integrin 6 expression that promotes tumor cell motility, acquisition of invasive traits such as MUC1, Bcl6, cathepsins, and UPA, and increases expression of MMPs." (PMID 36012631, 2022). "Disruption of Stat3 signalling leads to tumour-cell invasion through disruption of cell adhesion complexes, including E-cadherin, a crucial event of epithelial-mesenchymal transition in cancer." (PMID 35468857, 2022).
tumor (continued). "In view of the well-defined tumor-suppressing function of SOCS2 by inhibiting Jak2/Stat3 signaling, we detected the effects of miR-877-3p on Jak2/Stat3 signaling in GC." (PMID 35600882, 2022). "Stat3 functioning in immune cells in the tumor microenvironment further suppresses tumor immune surveillance to promote tumor progression." (PMID 35276290, 2022). "A large number of studies have shown that IL-6/JAK2/STAT3 signaling pathway is abnormally highly activated in many types of cancer and strongly inhibits anti-tumor immune response." (PMID 36591515, 2022). "Tumor proliferation is regulated by numerous genes or proteins, of which STAT3 and the downstream proteins participate in regulation." (PMID 36016565, 2022). "In normal cells, activation and inactivation of STAT3 are highly regulated, whereas, in tumor cells, STAT3 is typically overactive." (PMID 36557902, 2022). "Several cancer-derived cell lines depend on the constitutive activation of STAT3, which is overexpressed in tumor cells as a result of its phosphorylation by Janus kinases (JAKs)." (PMID 36015440, 2022). "This means that treatments based on STAT3 modulators should take into account the dual roles of this transcription factor and be tailored to specific tumor types." (PMID 36557902, 2022). "Among them, miR-30e-5p, a well-known tumor suppressor that suppresses tumorigenesis via the Sirt1/JAK/STAT3 signaling pathway, was downregulated in both AIS/MIA and invasive adenocarcinoma compared with benign PNs." (PMID 35366907, 2022). "In NSCLC sufferers, their serum and tumor samples comprised elevated quantities of STAT3-driven cytokines IL-6/11/22 and leptin and HGF growth factors." (PMID 36497125, 2022). "The IL-6/STAT3 pathway also affects the tumor-infiltrating immune cells in the TME in CRC and protects cancer cells from apoptosis." (PMID 36358769, 2022). "Taken together, these results indicated that STAT3 activation and tumor spheroid formation were sustained by LMO2 and LDB1." (PMID 36359204, 2022). "It is proved in many studies that CypB protected tumor cells from stress-induced apoptosis mostly through activation of STAT3 signaling pathway." (PMID 36266267, 2022). "STAT3-phosphorylated protein content was markedly elevated in the skeletal muscle of tumor-bearing mice compared to the controls." (PMID 35847939, 2022). "Compared with the Cur + miR-125a group, tumor growth was partially reversed in the Cur + miR-125a inhibitor + si-STAT3 group." (PMID 35942374, 2022). "CCL5 activates β-catenin/STAT3 signaling to promote the self-renewal and tumor metastasis of prostate CSCs (PCSCs), and its knockdown significantly inhibits the metastasis of prostate cancer and the self-renewal capacity of PCSCs." (PMID 35740975, 2022). "Studies have reported that the tumor cells with constitutive expression of STAT-3 maintain the activity of this pathway through positive autocrine feedback between IL-6 and the IL6R." (PMID 35465350, 2022). "We have shown that the combined inhibition of MEK and JAK/STAT3 pathway activity abrogates tumor properties in 3 different MB cell models in vitro as well as in 2 in vivo models of SHH MB." (PMID 35835937, 2022). "These gene signatures suggest that Niraparib effectively induces tumor cell apoptosis through STAT3 inactivation." (PMID 36324587, 2022). "Regulates the balance between “tumor-promoting bacteria” and “tumor-suppressing bacteria” and inactivated the NF-κB/IL-6/STAT3 pathway." (PMID 36051242, 2022). "STAT3 is a key element in multiple signaling pathways by promoting tumor progression, survival, tumor invasion, angiogenesis, and immunosuppression." (PMID 36531045, 2022). "WFDC2 has been shown to play vital roles in tumorigenesis, chemoresistance, and tumor metastasis and was confirmed to promote tube formation and enhance angiogenesis through STAT3 signaling (PMID: 32444701)." (PMID 35924143, 2022).
tumor (continued). "This is also supported by the positive correlation of STAT1 and STAT3 expression in human HCC samples in tumor and immune cells, indicating high immunological tolerance in a subset of HCC patients, as evident by PD-L1 expression." (PMID 35267462, 2022). "The activation of STAT3 helps tumor cells to evade NK cell-mediated immune surveillance, which is associated with high expression of tumor-promoting cytokines and growth factors, such as IL-10, TGF-β, and vascular endothelial growth factor-A." (PMID 36601109, 2022). "Stat3 is one of a family of cytoplasmic transcription factors that have important roles in tumor proliferation, metastasis and drug resistance." (PMID 35252007, 2022). "Stat3 inhibition also positively affects the tumor immunologic microenvironment by reducing the proportion of immunosuppressive cells." (PMID 35476809, 2022). "This directly impacts renal tumor progression as AKT inhibition attenuates tumor cell proliferation, while interference with STAT3 signaling blunts kynurenine-induced drug resistance and carcinoma cell migration." (PMID 35267539, 2022). "The IL-6/sIL-6R complex can bind to gp130 on tumor cells, activate the JAKs and STAT3 signaling and promote tumor cell proliferation and prevent apoptosis." (PMID 35954156, 2022). "At the moment, there is an unmet need to understand the effects of STAT3 inhibitors on NK-cell anti-tumor responses in vivo to be able to foresee the clinically relevant consequences." (PMID 35865518, 2022). "In this study, we discovered that that knockdown of Chemerin only partially inhibited JAK2 or STAT3 phosphorylation, indicating that Chemerin partially contributed to the tumor-promoting effect of neutrophils on OSCC cells." (PMID 35155249, 2022). "In tumor cells themselves, over-activated Stat3 reduces the expression of immunostimulatory factors by which exert profound immune effects." (PMID 36454780, 2022). "PRADX overexpression suppressed BLCAP expression via recruitment of H3K27me3, activating the phosphorylation of BLCAP interacting protein STAT3 and accelerating tumor metabolism and ATP production, resulting in tumor proliferation and poor survival outcomes." (PMID 35574370, 2022). "M2 macrophages can stimulate IL-8 secretion and promote the STAT3 signaling pathway in tumor progression." (PMID 36601121, 2022). "STAT5 and STAT3 signaling can promote tumor progression by regulating the expression of cell cycle, survival and proinflammatory genes." (PMID 35656514, 2022). "Collectively, these results suggest that PG can mediate tumor cell growth by downregulating STAT3 phosphorylation." (PMID 35496272, 2022). "The extent of STAT3 activation is affected by diet, and dieting is considered a potential therapy that promotes anti-tumor immunity." (PMID 35186730, 2022). "In a subset of tumors, co-localization of HER2 and activated STAT3 was evident in isolated tumor foci with IL-6 expressed in either adjacent tumor foci, adjacent stroma, or co-expressed with HER2 and pSTAT3." (PMID 35565421, 2022). "Therapeutic testing using STAT3 inhibitors have demonstrated promising results in some tumor diseases." (PMID 35326623, 2022). "After some time, however, astrocytes become the target of tumor-released factors which modify astrocytes towards a pro-tumoral program, for example maintained by the signal transducer and activator of transcription 3, STAT3." (PMID 36428520, 2022). "For example, in the mouse model of mucoepidermoid carcinoma, tocilizumab repression of STAT3 and AKT phosphorylation caused a significant decrease in tumour growth, drug resistance, and increased overall survival." (PMID 36429126, 2022). "GC-MSCs promote the activation of CD4+ T cells, which in turn, promote PD-L1 expression in GC-MSCs via p-STAT3 signaling, thereby promoting tumor growth." (PMID 36439438, 2022). "Receptor-related JAKs are well-known mediators of STAT3 phosphorylation for tumor development and inflammatory response." (PMID 35123491, 2022).